CD9 (CD9 molecule)
Diseases named in the same sentence as CD9 in open-access papers (continued):
Sharing a sentence is not in itself a finding about the gene and the disease.
colon carcinoma (25 papers, 2003 to 2025). "Thus, an anti-CD9 mAb (PAINS-13) that disrupts the association of CD9 with β1 integrin inhibited the growth of a human colon carcinoma cell line xenograft more effectively than another anti-CD9 mAb (VJI/20) or integrin mAbs." (PMID 29946318, 2018). "CD9 can inhibit the proliferation and tumorigenicity of human colon cancer cells in colorectal cancer." (PMID 40860827, 2025). "For instance, the examination of surgical tumor samples from patients with colon carcinoma indicated that CD9 was strongly expressed at the primary cells compared to those at metastatic sites in colon carcinoma." (PMID 36010551, 2022). "For example, the tetraspanin CD9 is downregulated in many human cancers including lung, breast and ovarian, and reduced CD9 expression is related to colon cancer metastasis." (PMID 34847198, 2021). "Anti-CD9 agonistic antibodies or ectopic expression of CD9 both exert an antiproliferative effect on human colon carcinoma cell lines." (PMID 29312336, 2017). "Previous examination of CD9 expression in certain cancers, including breast and colon cancers, has shown that metastases reduce CD9 levels compared with primary tumors." (PMID 24520284, 2014). "A positive correlation between CDCP1 and CD9 protein expression in colon cancer cell lines was demonstrated." (PMID 25301083, 2014). "CDCP1 and CD9 protein expression was measured in a series of colon cancer cell lines by flow cytometry and Western blotting." (PMID 25301083, 2014). "Interestingly, previous studies showed that reduced CD9 expression in primary tumor tissue was linked to poorer prognosis in CRC, while increased CD9 expression inhibited colon carcinoma cell growth." (PMID 39886381, 2025). "Interesting data have also been reported with anti-CD9 mAbs or Fab in leukemia and in colon cancer." (PMID 37046846, 2023). "In addition, tumor infiltrating CD56brightNK cells from breast and colon carcinomas highly express CD9 and CXCR3, similar to the reported exclusive expression of these cell surface markers by decidual NK cells as opposed to pNK cells of both subsets." (PMID 26079948, 2015). "Cell-surface CD9 was detected in all colon cancer cell lines with the exception of Colo320." (PMID 25301083, 2014). "Indeed, more than 30 CD9 partners have recently been identified in colon cancer cells; CD9 partners even differ between cell lines established from the primary tumour and the metastases obtained from a unique patient." (PMID 17848953, 2007). "The classification of colon cancers according to MRP-1/CD9, KAI1/CD82 and CD151 expression might be useful in identifying patients for whom intensive adjuvant therapy is warranted." (PMID 12838318, 2003). "One study on breast carcinomas, melanoma, and colon cancer tissues, where the majority of TINK cells belonged to the CD56brightCD16dim subset, demonstrated high expression of dNK cell markers CD9 and CXCR3 in the breast and colon tumors." (PMID 34209508, 2021). "CDCP1 and CD9 were co-expressed at the mRNA and protein level and we obtained evidence for the presence of a molecular complex of these proteins in SW480 colon cancer cells." (PMID 25301083, 2014). "As part of our evaluation of members of TM4SF as possible prognostic predictors, we further extended our study to the expression of CD151 and performed a retrospective study on the expression of CD151, MRP-1/CD9 and KAI1/CD82 in colon cancer." (PMID 12838318, 2003). "The aim of this study is to clarify the clinical significance of the member of TM4SF (MRP-1/CD9, KAI1/CD82 and CD151) in human colon cancer." (PMID 12838318, 2003). "We have shown that the reduction of MRP-1/CD9 and KAI1/CD82 expression, and the increasing CD151 expression are indicators for a poor prognosis in patients with colon cancer." (PMID 12838318, 2003).
colon carcinoma (continued). "The role of endogenous CD9 in cellular proliferation appears to depend on cellular context; it has been reported to activate EGFR signalling pathways (pro-proliferative) in gastrointestinal cancer cells, but to be anti-proliferative in human colon carcinoma." (PMID 28881726, 2017). "The expression of CDCP1 and CD9 proteins has not been extensively characterised in colon cancer cell lines." (PMID 25301083, 2014). "To investigate whether a monovalent Fab generated from mouse monoclonal CD9 Ab (clone 5H9) directed to human CD9 impedes EV-mediated morphological transformation of colon cancer cells, we used the established model of non-metastatic SW480 and highly metastatic SW620 cells." (PMID 36010551, 2022).
colorectal cancer (25 papers, 2011 to 2025). A primary or metastatic malignant neoplasm that affects the colon or rectum. "Studies on colorectal cancer have shown that moderately to highly differentiated tumor tissues exhibit increased Trop-2 expression, which is positively associated with CD9." (PMID 38794221, 2024). "However, CD9, another canonical EV marker protein, is associated with EGFR-positive EVs; most CD9-positive EVs are EGFR-positive in colorectal cancer cell DiFi, and approximately 74% of EGFR-positive EVs are CD9-positive in glioma cancer cell U373vIII." (PMID 37823055, 2023). "Moreover, we showed that the levels of 20S proteasomes in exosomes, MMP9+ and MMP9+/MMP2+/EMMPRIN+ exosome subpopulations in CD9-positive exosomes were significant for predicting colorectal cancer risk in CPPs." (PMID 33773551, 2021). "Indeed, in colorectal carcinoma, EpCAM and claudin-7 are found in association with the tetraspanins CD9 and/or CO-029 and promote metastasis formation." (PMID 21789222, 2011). "In colorectal cancer, the positive correlation between Trop-2 and CD9 expression opens up opportunities for combined targeted therapy strategies." (PMID 38794221, 2024). "A resent study confirmed that enhanced invasion and metastasis of colorectal cancer cells is the result of MMP-2 activation of the FAKTyr397/ERK pathway via the CD9-α7β1 integrin complex." (PMID 38389703, 2024). "For example, researchers discovered in colorectal cancer that Trop-2, Na+/K+ ATPase, CD9, PKCα, and cofilin assemble into a membrane signaling super complex, driving the growth and invasion of colorectal cancer." (PMID 39555080, 2024). "Protease cargo in CD9-positive blood plasma exosomes is prognostic biomarker for colorectal polyps and colorectal cancer." (PMID 33773551, 2021). "In fact, CD147, which is considered a biomarker for early-stage colorectal cancer, and CD9 double-positive EVs were also detected in samples with early-stage colorectal cancer that had invaded the submucosal layer by the ExoScreen assay." (PMID 31447954, 2019). "In contrast, a low CD9 expression on sEVs produced by colorectal cancer cells was shown to promote their uptake, which could be explained by the inactivating effect of CD9 on ADAM17-mediated adhesion of sEVs with α5β1 integrin on recipient cells." (PMID 39697985, 2023). "Moreover, induction of a proangiogenic and decidual-like CD56brightCD16dim/-CD9+CD49+ phenotype has also been observed in colorectal cancer patients." (PMID 35650630, 2022). "Nevertheless, other tetraspanin proteins, such as TSPAN8 and CD9, may promote cancer self-renewal in colorectal cancer and glioblastoma, respectively." (PMID 36193887, 2022). "Results using the ExoScreen assay from the same group showed that detection of CD145/CD9 dual positive cancer EVs is possible using 5 μL serum of colorectal cancer patients, and that EVs positive for GPRC5C/CD63 can discriminate pancreatitis patients from stage II pancreatic cancer." (PMID 31162490, 2018). "Interestingly, expression of CD9 (a member of tetraspanin superfamily, high expression of this tumor suppressor was connected to a favorable disease-free survival in colorectal cancer patients) was comparable with expression of CD9 detected in SW480 colorectal cancer cells." (PMID 40758205, 2025). "Using Random Survival Forest (RSF) analysis with importance scoring, we identified seven key prognostic genes (CD24, SLC25A5, HSPB1, CD9, SPIMK1, LGALS4, and CEACAM5), which were subsequently designated as the Colorectal cancer Survival Signature (CSS)." (PMID 40777020, 2025). "CD9 has been detected in microvesicles, and CD9+ EVs that contain CD147 have been detected in colorectal cancer patient sera." (PMID 36973758, 2023). "It was also found that the level of CD9 and another surface molecule CD147 was significantly increased in the serum of colorectal cancer patients." (PMID 35757760, 2022).
colorectal cancer (continued). "“ExoScreen” can detect CD9 and CD147 double positive EVs that are enriched in tissue culture media of colorectal cancer cells and serum from colorectal cancer patients." (PMID 28085080, 2017). "In the present study, we investigated the tetraspanin family proteins CD63, CD9 and CD81 as useful collection markers of exosomes derived from the three colorectal cancer (CRC) cell lines HCT-15, SW480 and WiDr." (PMID 22895844, 2012). "Our data reveal that monovalent CD9 Fab, but not divalent CD9 Ab, blocks the EV-mediated increase in malignancy of colorectal cancer cells." (PMID 36010551, 2022).
glioblastoma (25 papers, 2012 to 2025). The most malignant astrocytic tumor (WHO grade IV). "Various MR methods—including inverse variance weighted (IVW), weighted median (WM), and MR-Egger—were applied to assess the magnitude and direction of the association between CD9 expression and glioblastoma (GBM) risk." (PMID 40406701, 2025). "Among patients with glioblastoma, expression of CD9 by tumor cells has been reported to be associated with a poor prognosis." (PMID 29383115, 2017). "The Glioblastoma-EV-mediated release of EGFR mutant/variant III (EGFRvIII) in the context of CD9 tetraspanin may enhance glioblastoma progression, including cell invasion and angiogenesis." (PMID 38379858, 2024). "In glioblastoma, increased CD9 expression was associated with maintenance of glioblastoma stem-like cells, while CD81 was associated with enhanced resistance to radiotherapy by promoting nuclear translocation of RAD51, a protein involved in detection and repair of DNA double strand breaks." (PMID 36203458, 2022). "Another example is CD9, a gene encoding the transmembrane protein tetraspanin, which has been reported to be up-regulated and involved in tumor cell invasion, apoptosis, and resistance to chemotherapy from transcriptomic analysis of glioblastoma tissues compared to normal brain tissues." (PMID 27791206, 2016). "A trendof 3.9-fold lower levels for TNC+/CD9+ EVs inRTK-I glioblastoma patients was also observed when compared with themesenchymal (MES) subtype (p < 0.08)." (PMID 40056466, 2025). "Nonetheless, the significant differences observed in EVs fromboth plasma (by UC and SEC) and CSF samples support the potentialof TNC+/CD9+ EV quantifications as clinicalbiomarkers for glioblastoma, across different methods and liquid biopsysources." (PMID 40056466, 2025). "Single-cell RNA sequencing from 20 glioblastoma cases was analyzed using CellChat and Monocle3 to explore CD9-mediated cell communication and lineage transitions." (PMID 40406701, 2025). "Protein–protein interaction (PPI) network analyses and DsigDB drug predictions further identified CD9 as a therapeutic target, with emetine emerging as a promising candidate due to its reported anti-glioblastoma activity." (PMID 40406701, 2025). "In glioblastoma-infected individuals who obtain anti-survivin immunotherapy, the lower levels of CD9 +/SVN + and CD9 +/GFAP +/SVN + exosomes have been associated with the sustained survival of patients." (PMID 37965312, 2023). "The antiproliferative effect of CD9 was also observed in in vitro model of human glioblastoma executed via inhibition of EGFR phosphorylation." (PMID 37007105, 2023). "CD9 has been identified as a marker of CSCs also in the glioblastoma model, where its disruption led to decreased cell proliferation, invasion, and inhibition of tumor growth." (PMID 37007105, 2023). "A recent publication described in this context glioblastoma-derived EVs containing CD9 and CD81 in blood samples." (PMID 36203458, 2022). "CD9 has been described as a cancer stem cell marker in several types of cancers, including pancreatic cancer, glioblastoma, and B-acute lymphoblastic leukemia, and is related to the prognosis of AML." (PMID 33494824, 2021). "This is quite relevant to the field of EGFR research, as both EGFR and its glioblastoma mutant EGFRvIII can be found on Flotillin1+ sEVs extracted from the blood of glioblastoma and ovarian cancer patients, as well as on CD9+/CD81+ sEVs." (PMID 33302515, 2020). "For example, expression of CD9 gene and protein, a cell transmembrane molecule family mediating signal transductions, showed selective upregulation in human glioblastoma stem cell-like cells." (PMID 30092726, 2018). "CD9 silencing in three CD133+ glioblastoma cell lines (NCH644, NCH421k and NCH660h) led to decreased cell proliferation, survival, invasion, and self-renewal ability, and altered expression of the stem-cell markers CD133, nestin and SOX2." (PMID 26573230, 2016).
glioblastoma (continued). "We validated CD9 gene and protein expression showing selective up-regulation in glioblastoma stem cells isolated from primary biopsies and in primary organotypic glioblastoma spheroids as well as in U87-MG and U373 glioblastoma cell lines." (PMID 26573230, 2016). "Orthotopic xenotransplantation of CD9-silenced glioblastoma stem cells into nude rats promoted prolonged survival." (PMID 26573230, 2016). "In the present study, we performed transcriptomic analysis of glioblastoma tissues compared to normal brain tissues revealing sensible up-regulation of CD9 gene." (PMID 26573230, 2016). "Notably, CD9 is preferentially expressed in glioblastoma stem cells (GSCs) and is indispensable for maintaining their self-renewal capacity." (PMID 40406701, 2025). "Importantly,TNC+/CD9+ EVs significantly decreased in newlydiagnosed glioblastoma patients after tumor removal and reincreasedin the same individuals when the tumor recurred." (PMID 40056466, 2025). "Furthermore, within the astrocytoma and glioblastoma subgroups, high CD9 expression remained significantly correlated with worse outcomes." (PMID 40406701, 2025). "In glioblastoma, CD9 may further promote tumor cell migration and invasion by participating in extracellular vesicle-mediated processed." (PMID 40406701, 2025). "A clear CD9 signal was detected in all four glioblastoma cell lines." (PMID 36203458, 2022). "Moreover, CD9-silenced glioblastoma stem cells showed altered activation patterns of the Akt, MapK and Stat3 signaling transducers." (PMID 26573230, 2016). "Therefore, CD9 should be further evaluated as a target for glioblastoma treatment." (PMID 26573230, 2016). "In this instance, elevated TNC+ EV levels remained statistically significant in glioblastoma patientswhen compared to HD, particularly in the case of TNC+/CD9+ EVs (FC = 12.05, p < 0.01)." (PMID 40056466, 2025). "For CD9, its study in glioblastoma multiforme (GBM) revealed that the increase of CD9 and CD81 in extracellular vesicles (EVs) after radiotherapy was closely related to the cytotoxic response after treatment, which provided a new biomarker for radiotherapy monitoring." (PMID 40530955, 2025). "Immunostaining is accomplished with fluorescent antibodies against EV markers such as CD9, CD63, and CD81 or cancer markers, in this particular study from three glioblastoma cell lines overexpressing EGFRvIII, EGFR, or IDH1‐R132." (PMID 35898167, 2023). "In glioblastoma patients who receive anti-survivin immunotherapy, the low levels of CD9 + /SVN + and CD9 + /GFAP + /SVN + exosomes have been correlated with the sustained patient's survival." (PMID 36123730, 2022). "Despite many unresolved questions that we were not able to address so far, our data suggest the changed release of CD9 and CD81-positive EVs by glioblastoma as marker to monitor glioblastoma response to radiotherapy." (PMID 36203458, 2022). "After irradiation, however, the amount of CD9 and CD81-positive EVs increased in supernatant when glioblastoma cells underwent cell death, particularly apoptosis." (PMID 36203458, 2022). "We concluded that the amount of secreted CD9 and CD81-positive EVs correlated with cell death induction in glioblastoma cells 72 h after irradiation." (PMID 36203458, 2022). "Based on these observations, we concluded that specific proteins on extracellular vesicles such as CD9 and CD81 are excellent markers to monitor behavior of glioblastoma cells." (PMID 36203458, 2022). "Next, we employed flow cytometry to analyze CD9 and CD81 protein levels in cells of the four glioblastoma cell lines." (PMID 36203458, 2022). "They applied the designed assay to detect glioblastoma biomarkers CD-pan (CD9, CD63, and CD81), with EGFR, EGFRvIII and GAPDH as control markers, from supernatants of glioblastoma cells." (PMID 33276535, 2020).
glioblastoma (continued). "In ROC analysis, TNC+/CD9+ EVs exhibitthe greatest sensitivity and specificity values for glioblastoma detection.Finally, the concentration of TNC+/CD9+ EVswas also significantly elevated in CSF samples of glioblastoma patients,although with a lower fold change than in plasma samples." (PMID 40056466, 2025). "The number of CD9 or CD81-positive vesicles in supernatant of non-irradiated glioblastoma did not correlate with radiation-induced cytotoxicity in long-term or short-term assays." (PMID 36203458, 2022). "Moreover, we detected CD9 and CD81-positive EVs in the supernatant of all glioblastoma cells, although at different concentrations." (PMID 36203458, 2022). "Our experiments indicate that the amount of secreted CD9 or CD81-positive EVs did not correlate with the tetraspanin levels in glioblastoma cells." (PMID 36203458, 2022). "Therefore, we analyzed CD9 and CD81-positive EVs in the supernatant of glioblastoma cells 72 h after irradiation with photons or high LET protons, and compared the results to respective non-irradiated controls." (PMID 36203458, 2022). "We detected varying concentrations of CD9 or CD81-positive EVs in the supernatant of different glioblastoma cell lines, but could not use this data to predict the response to radiotherapy." (PMID 36203458, 2022). "We therefore concluded that the changed secretion of CD9 and CD81-positive EVs can be used to monitor glioblastoma cell response to radiotherapy irrespective of the radiation technique." (PMID 36203458, 2022). "Gene expression of both marker was significantly elevated in GBM as well as LGG samples compared to non-malignant samples, suggesting that expression on CD9 and CD81 was elevated early during cancer progression to glioblastoma." (PMID 36203458, 2022).